CST3 (cystatin C)
Diseases named in the same sentence as CST3 in open-access papers (continued):
Sharing a sentence is not in itself a finding about the gene and the disease.
prostate carcinoma (12 papers, 2009 to 2024). A carcinoma that arises from epithelial cells of the prostate gland. "There is also some evidence of increased expression of CST3 mRNA in higher-risk prostate cancer patients compared with those at lower-risk, but the utility of cystatin C (both serum and urine) requires further study." (PMID 38779086, 2024). "After limiting the follow-up duration, they found that cystatin C was the only biomarker that was negatively associated with the risk of prostate cancer." (PMID 36589819, 2022). "More recently, serum cystatin C has been proposed as a useful marker of increased osteoblastic activity associated to bisphosphonate treatments in prostate cancer patients with bone metastasis." (PMID 32180899, 2020). "In analyses excluding the first 4 years of follow-up, cystatin-C and phosphate were associated with prostate cancer risk." (PMID 32963348, 2020). "Our study uncovers a novel role for cystatin C and its associated cellular pathways in prostate cancer invasion and metastasis." (PMID 19956729, 2009). "More recently, serum cystatin C has been proposed as useful marker of increased osteoblastic activity associated to bisphosphonate treatments in prostate cancer patients with bone metastasis." (PMID 19956729, 2009). "We also identified multiple prostate cancer-associated genes such as cystatin C, PSCA, Cyp2e1, and dermatopontin that were remarkably underexpressed in CTRKO/LPB-Tag-CTRKO as compared to their WT and LPB-Tag counterparts, suggesting that CTR positively regulates these genes." (PMID 32180899, 2020). "After excluding the first 4 years of follow-up the 95% confidence intervals were wider and only cystatin-C and phosphate were associated with prostate cancer risk after controlling for multiple testing (HR per 1 SD increase 0.93, 0.89–0.97; and 1.07, 1.05–1.29, respectively)." (PMID 32963348, 2020). "However, the specific role of cystatin C protein expression in prostate cancer progression and its association with clinical characteristics has not been reported." (PMID 19956729, 2009). "However, the role of cystatin C in prostate cancer progression and its associated cellular and molecular networks remain to be investigated." (PMID 19956729, 2009). "Our findings suggest that loss of cystatin C and overexpression of AR may be two cooperative events in the progression of prostate cancer." (PMID 19956729, 2009). "Circulating cystatin C levels were higher in prostate cancer patients than in healthy blood donors (P = 0.0001) and in patients with BPH (P = 0.0078)." (PMID 36589819, 2022). "Previous study showed that the effect of CysC on modulating the prostate cancer cell invasion was provoked by crosstalk between cystatin C and AR-mediated pathways and Erk2 inhibitor that specifically inhibited MAPK/Erk2 activity." (PMID 36536031, 2022). "Well-known prostate cancer-associated genes such as PCA3, TMPRSS2, and CST3 were found to be upregulated in urinary sediment RNA from the higher-risk cancer group compared to those lower-risk group." (PMID 33363151, 2020). "Cystatin C has been suggested to play an important role in the neuroendocrine differentiation of prostate cancer." (PMID 32180899, 2020). "Benign ovarian cancers had significantly higher cystatin C levels than did malignant tumors; in prostate cancers, cystatin C levels also decreased at late stages." (PMID 21085595, 2010). "We examined cystatin C expression in three prostate cancer cell lines including the androgen-sensitive LNCaP cells and androgen-insensitive PC3 and DU-145 cells." (PMID 19956729, 2009). "The difference was statistically significant (p<0.001), suggesting that cystatin C protein expression is, in general, down-regulated in prostate cancer compared to benign epithelium." (PMID 19956729, 2009). "Taken together, our current data suggests an important role for cystatin C to inhibit prostate cancer cell invasion." (PMID 19956729, 2009).
prostate carcinoma (continued). "Virtually all benign specimens showed markedly high cytoplasmic protein expression of cystatin C while the matched prostate cancer tissues consistently displayed weaker or undetectable immunostaining." (PMID 19956729, 2009). "The present study aimed to evaluate the expression of cystatin C and its clinical relevance in prostate cancer, and to elucidate a novel role for cystatin C in prostate cancer invasion." (PMID 19956729, 2009). "Cystatin C has been suggested to play an important role in neuroendrocrine differentiation of prostate cancer." (PMID 19956729, 2009). "Meanwhile, cystatin C-positive neuroendocrine-like cells were stronger in prostate cancer than in benign tissues, suggesting a link between cystatin C and neuroendocrine differentiation in prostate cancer progression." (PMID 36589819, 2022). "Therefore, they concluded that preoperative cystatin C levels cannot be used for the early diagnosis of prostate cancer but can assist in predicting renal function in patients with prostate cancer." (PMID 36589819, 2022). "In prostate cancers, cystatin C levels remained high at early stages." (PMID 21085595, 2010). "Next, we assessed whether cystatin C knockdown might have effect on proliferation of prostate cancer cells." (PMID 19956729, 2009). "In conclusion, our studies provide, new insights into the mechanisms of cystatin C actions in prostate cancer cells, and may provide valuable information on cancer targets for therapeutic interventions." (PMID 19956729, 2009). "Thus, cystatin C may be used in combination with PSA to assist in the identification of prostate cancer in this ethnic group." (PMID 36589819, 2022). "Therefore, serum cystatin C may be an effective tumor marker for differentiating prostate cancer from benign prostate lesions." (PMID 36589819, 2022). "However, little is known about the precise mechanism of cystatin C function in prostate cancer." (PMID 19956729, 2009). "Because cystatin C was down-regulated in prostate cancer tissues and associated with increased expression of MMP2 that is known to contribute to tumor invasion and metastasis, we wanted to investigate the role of cystatin C expression in prostate cancer cell growth, survival and invasion." (PMID 19956729, 2009). "Although a direct link between cystatin C and extracellular matrix protein MMP2 in prostate cancer has been suggested, a precise role of cystatin C in prostate cancer progression has not been established." (PMID 32180899, 2020). "Here, we established for the first time a functional link between cystatin C and MAPK-Erk signalling and AR-mediated pathways in prostate cancer cells." (PMID 19956729, 2009). "Our present finding from the investigation of clinical materials indicates that there is a direct link between cystatin C and extracellular matrix protein MMP2 in prostate cancer." (PMID 19956729, 2009). "One of these studies involved cystatin C and prostate cancer, but no statistical significance was found." (PMID 36589819, 2022). "We have not investigated the role of cystatin C in modulation of cathepsin B activities in prostate cancer cells, however it is an open possibility considering the similar correlations in other type of tumors." (PMID 19956729, 2009).
chronic obstructive pulmonary disease (11 papers, 2014 to 2026). A chronic and progressive lung disorder characterized by the loss of elasticity of the bronchial tree and the air sacs, destruction of the air sacs wall, thickening of the bronchial wall, and mucous accumulation in the bronchial tree. "Low serum creatinine/cystatin C ratio (CCR) is associated with unfavorable characteristics in patients with chronic obstructive pulmonary disease (COPD); however, the relationship between CCR and in-hospital mortality of patients with acute exacerbation of COPD (AECOPD) is unexplored." (PMID 36104573, 2022). "Previous studies have shown that elevated serum creatinine/cystatin C ratio (CCR) is associated with various diseases, including chronic obstructive pulmonary disease (COPD), DM, non-alcoholic fatty liver disease, obstructive coronary artery disease and cancer as well as all-cause mortality." (PMID 35308546, 2022). "In recent years, many studies have discovered that cystatin C (Cys C) may play an important role in respiratory diseases, especially in chronic obstructive pulmonary disease (COPD)." (PMID 32586317, 2020).
endothelial dysfunction (11 papers, 2016 to 2026). In vascular diseases, endothelial dysfunction is a systemic pathological state of the endothelium (the inner lining of blood vessels) and can be broadly defined as an imbalance between vasodilating and vasoconstricting substances produced by (or acting on) the endothelium. "In some diseases, the relationship between the cystatin-C level and endothelial dysfunction was reported." (PMID 35877566, 2022). "Apart from being a more reliable parameter for estimating GFR, cystatin C correlates with subclinical inflammation and endothelial dysfunction, by various cardiometabolic pathways that may differ by sex." (PMID 41200622, 2025). "Regarding VSA, because endothelial dysfunction may be involved in the mechanism of VSA, cystatin-C may be a marker associated with coronary spasm, especially in MVS; however, whether this is a result or a cause remains to be seen." (PMID 35877566, 2022). "Interestingly, the inhibiting capacity of increased circulating cystatin C levels over the regenerative properties of the endothelial cells seems to alter the process of angiogenesis and induce endothelial dysfunction." (PMID 32962217, 2020). "Thus, all three parameters, i.e., circulating Ang-2, cystatin C and ADMA concentrations, rise in parallel with early renal impairment and endothelial dysfunction." (PMID 27893762, 2016).
peripheral artery disease (11 papers, 2012 to 2025). "The aim of this study was to investigate the relationship between serum cystatin C levels and peripheral arterial disease and to explore its diagnostic value for lower limb ischemia (LLI) in type 2 diabetic population." (PMID 23843968, 2013). "In our study, Cystatin C and the Cathepsin S/Cystatin C ratio proved to be significant determinants of severe peripheral arterial disease and three-arterial-bed involvement." (PMID 35453881, 2022). "Serum cystatin C (CysC) has been identified as a possible potential biomarker in a variety of diabetic complications, including diabetic peripheral neuropathy and peripheral artery disease." (PMID 27668262, 2016). "Although the present study couldn’t provide explicit answer to the detailed mechanism linking cystatin C and peripheral arterial disease, further follow-up and basic research will be carried out to reveal its related mechanism." (PMID 23843968, 2013). "Correlation of plasma CatS and cystatin C with aortic diameter and the lowest ABI suggest these serological parameters as biomarkers for human peripheral arterial diseases and AAA." (PMID 22844527, 2012).
renal fibrosis (11 papers, 2017 to 2024). A final common manifestation of a wide variety of chronic kidney diseases characterized by glomerulosclerosis and tubulointerstitial fibrosis. "Classic biomarkers of CKD such as serum creatinine (Scr), blood urea nitrogen (BUN), and cystatin C (Cys-c) are incapable of accurately diagnosing renal fibrosis." (PMID 31485275, 2019). "In addition, Scr, BUN, cystatin C, eGFR, and 24 h proteinuria had no statistical significance in the correlation with renal fibrosis by the stepwise multivariate logistic regression analysis." (PMID 35222740, 2022).
type 1 diabetes (11 papers, 2019 to 2026). "Clinically, a higher level of serum cystatin C was associated with decreased insulin sensitivity in type 1 diabetic patients." (PMID 34899825, 2021). "In backwards multivariable regression on total study population, age, sex, type 1 diabetes diagnosis, BMIz and BP z scores, HbA1c and cystatin C were used as independent variables." (PMID 41219438, 2026). "QTVI correlated with type 1 diabetes duration, longitudinal HbA1c AUC and cystatin C in children with type 1 diabetes at baseline, and with CV at follow-up." (PMID 41219438, 2026). "Cystatin C was positively correlated with HbA1cAUC, CV, type 1 diabetes duration and age (HbA1cAUC, r=0.404, p<0.01; CV, r=0.381, p=0.041; type 1 diabetes duration, r=0.342, p=0.025; age, r=0.397 p=0.008) and negatively correlated with TIR (r=–0.476, p=0.009)." (PMID 41219438, 2026). "In a sub-group of patients with type 1 diabetes blood was drawn at time of and after diagnosis, with a mean time between samplings 1.3 ± 0.5 years (n = 42), the trajectory of circulating Cystatin C, MMP-9, lipocalin-2 and FGF21 was analysed." (PMID 38932813, 2024). "The connection found between cystatin C and QTVI is also consistent with previous studies wherein CAN has been associated with increased albuminuria and decreased GFR in both adolescents and adults with type 1 diabetes." (PMID 41219438, 2026). "In addition, cystatin C has been shown to be more accurate at detecting a rapid decline in GFR than creatinine measurements among participants with type 1 diabetes who have normal GFR levels." (PMID 37128173, 2023). "In a large cohort of patients with type 1 diabetes, serum cystatin C levels was more sensitive for identifying early decline in kidney function and better associated with glomerular filtration rate than serum creatinine levels and creatinine-based estimated GFR formulae." (PMID 33401560, 2021). "The first aim of this study was to investigate plasma levels of FGF21, Cystatin C, lipocalin 2 and MMP-9 in children and adolescents with different duration of type 1 diabetes." (PMID 38932813, 2024). "Increased cystatin C and disorders of lipid metabolism are associated with a higher risk of cardiovascular diseases (CVD), which are the leading cause of mortality in patients with type 1 diabetes (T1D)." (PMID 35208542, 2022). "This study aimed to investigate plasma levels of FGF21, Cystatin C, lipocalin-2, and MMP-9 in children and adolescents with different duration of type 1 diabetes and possible correlation to HbA1c to identify potential biomarkers of future complication development." (PMID 38932813, 2024).
hyperlipidemia (10 papers, 2015 to 2025). "We demonstrated that deletion of apoE per se was associated with hyperlipidemia via elevations in plasma levels of both cholesterol and triglycerides; however, little consequent effect on urinary albumin excretion, plasma cystatin C levels or glomerular matrix accumulation were observed." (PMID 32581831, 2020). "The study found that age, stage IV, hyperlipidemia and hypothyroidism were significantly and independently related to the risk of CSVD, while also revealing a correlation between PLR、SII and elevated cystatin C levels with CSVD." (PMID 40933994, 2025). "The eGFR is a calculation indicator based on serum (plasma) creatinine and/or cystatin C. The level of serum creatinine is easily affected by muscle quality, dietary protein intake, hyperlipidemia, hemolysis, and the method of detection (Jaffe’s method or enzymatic method)." (PMID 36531487, 2022).
hypothyroidism (10 papers, 2016 to 2025). Abnormally low levels of thyroid hormone. "Intracellular metabolism is suppressed in patients with hypothyroidism, leading to decreased cystatin C secretion from nucleated cells." (PMID 38416371, 2024). "Additionally, transforming growth factor beta-1, which stimulates vascular smooth muscle cells to secrete cystatin C, is significantly reduced in hypothyroidism." (PMID 38416371, 2024). "However, it should be noted that high doses of glucocorticoids increase the formation of cystatin C, as well as that cystatin C values are reduced in hypothyroidism and elevated in hyperthyroid states." (PMID 38125620, 2024). "However, serum cystatin C is lower under the condition of hypothyroidism in contrast with serum creatinine." (PMID 37184818, 2023). "Despite the increase of s-Cr levels, serum cystatin C levels were normal, which could be explained by the hypothyroidism." (PMID 32234009, 2020).
injury (10 papers, 2017 to 2023). Damage inflicted on the body as the direct or indirect result of an external force, with or without disruption of structural continuity. "The cystatin C concentrations in the serum and urine are known to increase 12–24 h after the onset of kidney injury." (PMID 30039479, 2018). "In addition to these classic biomarkers, the newest ones have shown promising results for the diagnosis of early-stage kidney injury: cystatin C, KIM-1, NAG, NGAL, β2-microglobulin, osteopontin, TIMP-1, GST-α, without being implemented in clinical practice." (PMID 36676974, 2022). "Cystatin C, a novel serum biomarker that rises in the setting of kidney injury, may be a better surrogate marker for assessing kidney function in patients with liver impairment." (PMID 30188943, 2018). "Importantly, in previous studies, the levels of cystatin C increased with the progression of renal damage, making it suitable for early detection of kidney injury and accurate assessment of DKD." (PMID 29854459, 2018). "Moreover, in critically ill neonates, cystatin C could be used as a powerful predictor of kidney injury." (PMID 36589822, 2022). "The Ccr, serum cystatin C level, urinary NAG activity, and microalbuminuria/creatinine ratio were detected to reflect kidney injury." (PMID 28814987, 2017).
malnutrition (10 papers, 2019 to 2025). Inadequate nutrition resulting from poor diet, malabsorption, or abnormal nutrient distribution. "We suggest to evaluate plasma creatinine (and cystatin C in case of malnutrition), urinalysis and blood pressure." (PMID 40091088, 2025).
colon cancer (9 papers, 2004 to 2025). "Moreover, in the present study, the authors show that after adjustment for cystatin C the association between ProCT and colon cancer in men remained statistically significant, suggesting a specific relationship between cancer and ProCT levels in spite of renal function." (PMID 23984981, 2013). "It is worth noting that the creatinine/cystatin C ratio can perform good prognostic differentiation on rectal cancer (50.8% vs 68.8%, p=0.003) and colon cancer (54.1% vs 69.0%, p=0.009)." (PMID 37409249, 2023). "After additional adjustment for BMI, smoking, hsCRP and cystatin C the association between PCT and colon cancer incidence in men remained statistically significant (HR per 1 SD PCT increment (95% CI) = 1.45 (1.03 to 2.04); P = 0.034)." (PMID 23937962, 2013). "To examine the underlying mechanism(s) by which CST1 increases tumor growth, we monitored the primary growth of CST1- and CST3-overexpressing colon cancer cells using a xenograft assay." (PMID 24357805, 2013). "Furthermore, the high creatinine/cystatin C ratio was a prognostic factor for poor PFS/OS in patients with colon cancer." (PMID 37409249, 2023). "Furthermore, it was suggested that cystatin C and cathepsin B interaction may participate in the modulation of the invasive phenotype of human colonic tumours." (PMID 15138478, 2004). "We next determined the role of CST1 upregulation in colon cancer and the function of the interaction between CST1 and CST3 in the extracellular space." (PMID 24357805, 2013).
gastric cancer (9 papers, 2013 to 2025). A primary or metastatic malignant neoplasm involving the stomach. "Cystatin C was also significantly associated across each type of GI cancer whereas race is associated with all GI cancers except gastric cancer." (PMID 38263244, 2024). "A diminished Creatinine/Cystatin C ratio (CCR) has been correlated with unfavorable prognoses in gastric cancer patients." (PMID 38706605, 2024).